IL10 (interleukin 10)
Diseases named in the same sentence as IL10 in open-access papers (continued):
Sharing a sentence is not in itself a finding about the gene and the disease.
inflammatory bowel disease (413 papers, 2005 to 2026). A spectrum of small and large bowel inflammatory diseases of unknown etiology. "Interleukin‐10 (IL‐10) signaling is critical for intestinal immune homeostasis, and defects in this pathway underlie infantile‐onset inflammatory bowel disease (IOIBD)." (PMID 41425514, 2025). "As IL-2 responsiveness is important for IL-10 induction in CD4+ T cells, patients with CD25 deficiency share severe and early onset inflammatory bowel disease with patients suffering from IL-10 or IL-10R (IL-10RA or IL-10-RB) deficiency." (PMID 38507159, 2024). "IL10 and IL10 receptor deficiencies lead to severe intestinal inflammation and early-onset inflammatory bowel disease in both mice and humans, highlighting the importance of IL10 signaling in maintaining intestinal mucosal homeostasis." (PMID 39337678, 2024). "IL-10 is a regulatory cytokine that has been widely shown to limit immunopathology particularly during infection and intestinal responses to pathobionts and mutations in IL-10 or the IL-10R result in inflammatory bowel disease (IBD) in humans." (PMID 38074197, 2023). "IL-10R mutations associated with inflammatory bowel disease (IL-10 and IL-10 receptor mutations in very early-onset inflammatory bowel disease) lead to the loss of the inhibitory effect of IL-10 on proinflammatory cytokine production in patient cells." (PMID 37373318, 2023). "Very early-onset inflammatory bowel disease (VEOIBD) with interleukin-10 (IL10R) signaling deficiency usually requires enterostomy in patients who are refractory to traditional treatment." (PMID 37986047, 2023). "IL-10 expression was found lower in psoriatic and asthmatic patients and IL-10 and IL-10R mutations, causing a loss of IL-10 function, were found to be associated with severe inflammatory bowel disease, including Crohn’s disease and ulcerative colitis." (PMID 37359549, 2023). "In fact, IL-10 deficiency both in mice and humans is related to inflammatory bowel disease and cancer." (PMID 37629156, 2023). "IL-10 signaling has been particularly important for tolerance induction in the gut, as patients with loss of function mutations in IL-10 or IL-10R develop very early onset severe inflammatory bowel disease." (PMID 35493508, 2022). "Balish and Warner found that the inoculation of Enterococcus faecalis causes chronic, progressive inflammatory bowel disease in germ-free IL-10-knockout mice." (PMID 35433775, 2022). "Loss of function mutations affecting any of the two genes encoding interleukin-10 receptor (IL10RA or IL10RB genes); or affecting the gene encoding the cytokine IL-10 (IL-10 gene), will cause early-onset inflammatory bowel disease." (PMID 32737687, 2020). "Interleukin-10 (IL10) signalling pathway deficiency results in severe very early onset inflammatory bowel disease (VEOIBD), and enterostomy is often inevitable." (PMID 31931724, 2020). "A defect of IL-10 or the IL-10 receptor has been linked to excessive immune reactions and a disposition to chronic inflammatory disease, such as the early onset of inflammatory bowel disease." (PMID 32849644, 2020). "In murine models of inflammatory bowel disease, the frequency of DNA mutations in the colon was 4- to 5-fold greater in IL-10 deficient mice than in IL-10-sufficient mice." (PMID 32039024, 2019). "IL-10 deficiency in mice can lead to the development of spontaneous inflammatory bowel disease and IL-10 receptor mutations found in patients result in an early-onset enterocolitis." (PMID 31396220, 2019). "In this section we discuss diseases with a distinc phenotype of inflammatory bowel disease including the “IL-10 group” of IL-10 and IL-10 receptor alpha and beta deficiency as well as the haploinsufficincy of NFAT5." (PMID 31799221, 2019). "Blocking the IL-10 pathway in mice causes spontaneous development of inflammatory bowel disease (IBD)." (PMID 31244763, 2019).
inflammatory bowel disease (continued). "In particular, IL-10 is critical to maintain the goblet cell production of mucins, and the mutations in IL-10 receptors resulted in inflammatory bowel diseases." (PMID 30233555, 2018). "Amongst these are the first recognized monogenic causes of such diseases, namely interleukin-10 (IL-10) and IL-10 receptor (IL-10R) loss of function mutations that are the specific cause of a severe, very early onset type of inflammatory bowel disease." (PMID 30809233, 2018). "The association between IL-10 and inflammatory bowel disease has been demonstrated in both humans and in animal models." (PMID 30159141, 2018). "The IL-10-knockout mouse model of inflammatory bowel disease (IBD) is a useful tool to analyze the mechanisms underlying IBD." (PMID 29212210, 2017). "IL10-deficient mice are sensitive to chemically induced carcinogenesis and spontaneously develop inflammatory bowel disease, which is associated with the occurrence of colon carcinomas." (PMID 26956044, 2016). "Mouse models of IL-10 deficiency develop inflammatory bowel disease upon colonization of the gut with particular microorganisms, whereas in humans, genetic studies have confirmed the essential role of IL-10 in preventing deleterious inflammation in the gut." (PMID 27881137, 2016). "IL-10 is an important dampener of immune responses in the intestine, and loss of IL-10 or its receptor (IL-10R) results in early-onset inflammatory bowel disease in humans (Ref." (PMID 27341512, 2016). "Mice that were deficient in IL-10 spontaneously developed inflammatory bowel disease (IBD), which later progressed to colorectal carcinoma." (PMID 26217588, 2015). "Inflammatory bowel disease in infants and children has been associated with IL-10 and IL-10R deficiencies, chronic granulomatous disease, immunedysregulation-polyendocrinopathy-enteropathy-X-linked syndrome (IPEX), autoinflammatory disorders, and others." (PMID 25999944, 2015). "We report here that peritoneal injection of IL-33 exacerbated inflammatory bowel disease in IL-10-deficient (IL-10−/−) mice, whereas IL-33-treated IL-10-sufficient (wild type) mice were protected from the disease induction." (PMID 24491821, 2014). "The crucial role of IL-10 in the prevention of inflammatory bowel disease has been demonstrated by experiments in IL-10-deficient mice and daily systemic administration of recombinant IL-10." (PMID 24971344, 2014). "The importance of IL-10 has been further underscored by the finding that knockout of IL-10 in mice causes inflammatory bowel disease due to a deregulated immune response to the gut flora." (PMID 23533666, 2013). "Several cytokines are essential to maintain tolerance to the gut microbiota, as evidenced by the association of IL-10, FoxP3 or TGFβ1 function in mice or humans with inflammatory bowel disease (IBD) or autoinflammatory disorders." (PMID 22624013, 2012). "Both overexpression (e.g., in lymphoma) as well as IL-10 deficiency (e.g., in inflammatory bowel disease) are likely to have a physiological significance." (PMID 21991534, 2011). "The interleukin-10 gene-deficient (Il10−/−) mouse is a well-established model of human inflammatory bowel disease (IBD) and used to study the complex host-environment (e.g., diet, bacteria) interactions and the action of potential therapeutics." (PMID 20671959, 2010). "On the contrary, there have been many studies that find genetic associations of the IL-10 polymorphisms with inflammatory diseases like rheumatoid arthritis, type 1 diabetes, systemic lupus erythematosus or inflammatory bowel diseases." (PMID 16803619, 2006). "Genetic deficiency in the expression of interleukin-10 (IL-10) is associated with the onset and progression of experimental inflammatory bowel disease (IBD)." (PMID 16259632, 2005). "IL‐10, an essential anti‐inflammatory cytokine, is vital for immune homeostasis; its deficiency may result in severe inflammatory bowel diseases." (PMID 39830908, 2025).
inflammatory bowel disease (continued). "The anti‐inflammatory cytokine interleukin‐10 (IL‐10) modulates sphingolipid metabolism to attenuate nuclear factor kappa‐light‐chain‐enhancer of activated B cells (NF‐κB)‐mediated inflammation, thereby increasing the risk of inflammatory bowel disease." (PMID 40895135, 2025). "Several genome-wide association studies have linked mutations in the IL-10 signaling pathway with inflammatory bowel diseases in humans, and previous studies in mice have shown that blocking IL-10 signaling can alter the differentiation of H. hepaticus-specific T cells from TREG cells to TH17 cells." (PMID 41279934, 2025). "H. hepaticus causes inflammatory bowel disease in IL-10-deficient mice." (PMID 39019114, 2024). "Loss of IL-10 signalling results in life-threatening inflammatory bowel disease in humans and mice—however, the exact mechanism by which IL-10 signalling subdues inflammation remains unclear." (PMID 38383790, 2024). "Finally, impaired IL-10 signaling causes the accumulation of damaged mitochondria in macrophages, which adds to the dysregulated inflammatory response seen in patients with inflammatory bowel disease." (PMID 38790796, 2024). "A previous study, which used interleukin 10-deficient mice crossed with MUC1.Tg mice that developed spontaneous inflammatory bowel disease, showed that vaccination with a Tn-MUC1 100-mer peptide could reduce inflammation." (PMID 36980805, 2023). "Humans with mutations in IL‐10 signaling manifest with severe inflammatory bowel diseases." (PMID 35695080, 2022). "Loss of IL-10 signaling in macrophages (Mφs) leads to inflammatory bowel disease (IBD)." (PMID 31819956, 2020). "Soon after the cytokine IL-10 was cloned, we generated a mouse mutant deficient for IL-10 and could show that these mice developed inflammatory bowel disease that depended on the microflora." (PMID 32849644, 2020). "This could help to explain the development of early onset Inflammatory Bowel Disease in patients with IL-10 deficiency." (PMID 31509557, 2019). "Inflammatory bowel disease was observed in mice deficient with IL-10." (PMID 31490973, 2019). "Interestingly, the association between AHR, IL10, and inflammatory bowel disease, together with 19 other TF–cytokine-disease associations was absent in predictions based on PDIs from the union of TRRUST and InnateDB." (PMID 30184180, 2018). "Indeed, germline LOF mutations in the genes coding for IL-10 or IL-10R are a major cause of early onset inflammatory bowel disease, demonstrating a critical requirement for IL-10 signaling (presumably through STAT3) to maintain tolerance in the bowel." (PMID 29472924, 2018). "Similarly, polymorphisms in the human IL-10–IL-10R axis are associated with susceptibility to inflammatory bowel disease." (PMID 28265004, 2017). "Genetic analysis in the IL10-deficient mouse model revealed a modifier locus of experimental inflammatory bowel disease (IBD) on chromosome 18, with the allele of the strain C3H/HeJBir (C3Bir) conferring resistance and the allele of C57BL/6J (B6) conferring susceptibility." (PMID 27191968, 2016). "This role of IL-10 is vitally important in protecting the host from infection-associated immunopathology, autoimmunity, and allergy, such as sepsis, arthritis, insulitis, inflammatory bowel disease (IBD), and so on." (PMID 26918147, 2015). "IL-10 produced by several innate and adaptive immune cells is a key immunosuppressive and anti-inflammatory cytokine as illustrated by the spontaneous lethal inflammatory bowel disease of IL-10-deficient mice." (PMID 23226238, 2012). "In inflammatory bowel diseases, disturbed adrenergic regulation of interleukin-10 (IL-10) could be part of the mechanism underlying the modulation of disease activity due to psychological stress." (PMID 18983682, 2008). "Loss of IL-10 leads to the development of spontaneous inflammation such as inflammatory bowel disease (IBD) or similar colonic inflammation in mice." (PMID 40293552, 2025).
inflammatory bowel disease (continued). "For example, we observed that a cis-pQTL for IL-10 was also associated with risk of inflammatory bowel disease (IBD), with the allele associated with higher plasma IL-10 correlating with reduced IBD risk, consistent with the anti-inflammatory effects of IL-10." (PMID 37563310, 2023). "Interestingly, some of these mediators such as IL-6 and TNF-α are involved in the pathogenesis of inflammatory bowel disease, promoting gut damage and loss of intestinal barrier integrity, while IL-10 reduces the inflammation typically associated with this pathology." (PMID 35854319, 2022). "While the protective role of IL-10 is relatively well established in the context of inflammatory bowel disease (IBD) and other inflammatory diseases, its role in susceptibility to infections is less well understood." (PMID 35603217, 2022). "Genetic forms of inflammatory bowel disease (IBD) are caused by mutations in genes that are involved in the IL-10 signaling pathway." (PMID 36466870, 2022). "Further, a lower concentration of Bifidobacterium species is associated with fewer interleukin-10-secreting dendritic cells in inflammatory bowel disease (IBD)." (PMID 34684597, 2021). "It has been reported that lost function of the IL-10 signaling pathway, i.e., loss-of-function mutations in IL-10 and IL-10 receptors, causes severe early-onset inflammatory bowel disease (IBD)." (PMID 33535645, 2021). "For example, IL10 deficient patients develop severe infantile-onset inflammatory bowel disease (IBD)." (PMID 33490091, 2020). "Nucleotide sequence alterations in IL10 are linked with the risk of developing inflammatory bowel disease (IBD), as reported in genome wide association studies." (PMID 29755507, 2018). "The mouse pathobiont Helicobacter hepaticus can induce typhlocolitis in interleukin-10-deficient mice, and H. hepaticus infection of immunodeficient mice is widely used as a model to study the role of pathogens and commensal bacteria in the pathogenesis of inflammatory bowel disease." (PMID 23951007, 2013). "Studies showed that the genetic modification of probiotics to generate anti-inflammatory cytokines including IL-10 or IL-35, successfully regulates inflammatory bowel disease (IBD) along with enhancing the restoration of immune equilibrium." (PMID 41550964, 2026). "Despite its therapeutic potential, systemic delivery of IL-10 has failed in clinical trials for inflammatory bowel disease (IBD), largely due to its poor localization and short half-life." (PMID 42076094, 2026). "This study aimed to evaluate the effects of milk kefir on parameters related to inflammatory bowel disease (IBD) in interleukin-10 knockout (IL-10-/-) mice." (PMID 41665242, 2026). "IL-10 plays an important function in inflammatory bowel disease by limiting excessive inflammatory responses and promoting tissue repair." (PMID 40542404, 2025). "rs1800896 (IL10) and rs1143634 (IL1B) have been associated with rheumatoid arthritis and inflammatory bowel disease." (PMID 41346622, 2025). "In human inflammatory environments such as pathogenic bacterial infection and inflammatory bowel disease, it activates AKT and promotes IL10 secretion, thereby, alleviating inflammation." (PMID 41497808, 2025). "The IL-10/IL-10 axis plays a crucial protective role in autoimmune disorders, as illustrated in conditions like MS and inflammatory bowel disease (IBD)." (PMID 39592739, 2025). "Identifying a specific gene required for the ability of B. theta to induce IL-10 provides a promising target to be used in generating probiotics to treat inflammatory diseases such as inflammatory bowel disease." (PMID 39868786, 2025). "Inflammatory bowel disease: Blimp-1 is required for IL-10-mediated antioxidant responses and is important in regulating immune cell metabolism and in the control of inflammation, including in IBD." (PMID 40002370, 2025).
inflammatory bowel disease (continued). "The mucosal administration of IL-27 was reported to exert beneficial effects in murine models of inflammatory bowel disease, through its capacity to modulate macrophage function that regulates T cell activation and IL-10 production." (PMID 40141330, 2025). "Produces and delivers IL-10 in vivo and regulates immune responses offering therapeutic benefits for inflammatory diseases such as inflammatory bowel disease (IBD) and ulcerative colitis." (PMID 38543481, 2024). "IL-6, TNF-α, IL-1β, and IL-10 serve as pivotal pathological mediators in inflammatory bowel disease." (PMID 39187810, 2024). "A sour understanding of the contributions of IL-17-producing Treg and IL-10-producing Th17 in these diseases continues to expand, their associations with conditions such as inflammatory bowel disease (IBD), cancer, nephritis, autoimmune disorders, and others are gradually being unveiled." (PMID 38317142, 2024). "Applied to humans, FMT in patients with inflammatory bowel diseases resulted in increased IL-10 production and a decrease in IL-17 blood level." (PMID 38339169, 2024). "In an animal model of inflammatory bowel disease, the colonic smooth muscle of IL-10 knockout mice showed decreased contractility relative to the colonic smooth muscle of wild-type IL-10 mice." (PMID 38978990, 2024). "GRN competitively binds with TNFR1/2 to disrupt TNF-α function, which in turn leads to increased IL-10 production in T regulatory cells in conditions such as rheumatoid arthritis and inflammatory bowel disease." (PMID 39143467, 2024). "It has been shown that microbiota transplantation in patients with inflammatory bowel diseases leads to an increase in the production of IL-10 and a decrease in IL-17 in the blood." (PMID 38339169, 2024). "FDEVs reduce pro-inflammatory cytokines (IL-1β, IL-6) and increase anti-inflammatory IL-10 levels, demonstrating efficacy in mouse models of inflammatory bowel disease." (PMID 39796048, 2024). "Lastly, we found that ulcerative colitis (UC) and inflammatory bowel disease (IBD) were related to IL-10 responses through the cis-regulation of IL10 locus." (PMID 38714679, 2024). "For example, pre-clinical studies investigating the administration of IL-10 or IL-10 receptor agonists have shown promising results in inflammatory bowel disease (IBD), where excessive pro-inflammatory cytokines play a significant role in disease pathogenesis." (PMID 38251210, 2024). "Further in line with our findings, another study illustrated that the expression of IL‐10 is increased after γ‐Res treatment in inflammatory bowel disease." (PMID 38372468, 2024). "In humans and mice, IL10 was found to have a crucial role in the prevention of inflammatory bowel disease (IBD)." (PMID 36814903, 2023). "Very early-onset inflammatory bowel disease (VEOIBD), caused by defects in interleukin-10 (IL-10) signaling, including defects in IL10, IL10RA, and IL10RB, is an autosomal recessive disorder." (PMID 37986047, 2023). "IL-10 appeared to have an inhibitory effect on the synthesis of pro-inflammatory cytokines released from T lymphocytes and macrophages in active inflammatory bowel disease, and the administration of IL-10 to patients with UC reduces their complaints." (PMID 37762896, 2023). "The potent suppressive function of IL-10 is illustrated by the development of very early onset inflammatory bowel disease (VEO-IBD), defined as presentation of IBD in children <6 y of age, among patients with monogenic variants in IL-10 or its receptors." (PMID 37314833, 2023). "It has been shown that individuals with severe immune-mediated diseases, such as very early onset inflammatory bowel disease (VEOIBD) and autoimmune thyroid diseases, have polymorphisms in IL-10 and its receptors, IL-10RA and IL-10RB." (PMID 36992353, 2023). "This is in line with the reported ability of IL-10 in downregulating excessive inflammation in allergic airway inflammation, inflammatory bowel disease, rheumatoid arthritis, etc.." (PMID 37443161, 2023).